SERPINB13 (serpin family B member 13)
Description:
May play a role in the proliferation or differentiation of keratinocytes.
Synonyms: PI13; HUR7; HSHUR7SEQ; headpin
Tractability: No criterion of Open Targets' tractability assessment is met for any kind of drug.
Gene: Protein-coding gene on chromosome 18 (63,586,989 to 63,604,639, forward strand). Ensembl gene ENSG00000197641.
Subcellular location: Cytoplasm
Subcellular location (Human Protein Atlas): Cytosol; Nuclear speckles
Pathways (Reactome):
Gene expression (Transcription): RUNX1 regulates transcription of genes involved in differentiation of keratinocytes
Gene Ontology:
Molecular function: cysteine-type endopeptidase inhibitor activity; protease binding; protein binding; serine-type endopeptidase inhibitor activity; endopeptidase inhibitor activity
Biological process: negative regulation of endopeptidase activity; negative regulation of keratinocyte apoptotic process; regulation of proteolysis; response to UV
Cellular component: cytoplasm; cytosol; extracellular exosome; nucleolus; nucleoplasm; lysosomal lumen
Genetic constraint (gnomAD): Loss-of-function variants: 21 observed, 26.55 expected, observed/expected ratio (o/e) 0.79, 90% interval 0.56 to 1.14. The upper end of that interval is the gene's LOEUF score, 1.14, which puts it in group 4 of 6, group 1 being the genes least tolerant of losing a copy. Missense variants: 447 observed, 443.91 expected, observed/expected ratio (o/e) 1.01, 90% interval 0.93 to 1.09. Synonymous variants: 174 observed, 163.34 expected, observed/expected ratio (o/e) 1.07, 90% interval 0.94 to 1.21.
Homologues: Orthologues: chimpanzee SERPINB13 (98% identical), macaque SERPINB13 (95% identical), rabbit SERPINB13 (82% identical), pig SERPINB13 (80% identical), dog SERPINB13 (79% identical), mouse Serpinb13 (75% identical), rat Serpinb13 (74% identical), guinea pig SERPINB13 (73% identical). Paralogues in human: SERPINB4 (58% identical), SERPINB3 (58% identical), SERPINB1 (46% identical), SERPINB10 (45% identical), SERPINB12 (44% identical), SERPINB6 (43% identical), SERPINB11 (42% identical), SERPINB9 (42% identical), SERPINB2 (40% identical), SERPINB8 (39% identical), SERPINB7 (38% identical), SERPINC1 (35% identical), and 24 more.
Diseases named in the same sentence as SERPINB13 in open-access papers:
SERPINB13 is named in the same sentence as 24 diseases in open-access papers, as found by Europe PMC text mining. Sharing a sentence is not in itself a finding about the gene and the disease. The quoted sentences say what the papers report.
psoriasis (5 papers, 2015 to 2025). An autoimmune condition characterized by red, well-delineated plaques with silvery scales that are usually on the extensor surfaces and scalp. "Decision curve analysis (DCA) demonstrated that the nomogram provided superior clinical utility in predicting psoriasis occurrence probability at a high-risk threshold of 0–1, compared to individual curves for S100A7, SERPINB13, and PLBD1." (PMID 38699235, 2024). "However, in diseased skin, SERPINB13 was significantly overexpressed and redistributed, indicating its potential involvement in the pathogenesis of psoriasis." (PMID 38699235, 2024). "Interestingly, our study also revealed that SERPINB13 is a key regulator of psoriasis, as evidenced by its rapid decrease in expression following dithranol treatment in psoriatic patients." (PMID 38699235, 2024). "Both SerpinB3 and SerpinB13 are highly expressed in psoriasis lesions." (PMID 39737188, 2024). "We revealed 479 differentially expressed genes between secukinumab and Dead Sea climatotherapy at the end of treatment, with a psoriasis panel identifying SERPINB4, SERPINB13, IL36G, IL36RN, and AKR1B10 as upregulated in Dead Sea climatotherapy compared with secukinumab." (PMID 38892277, 2024). "Our findings indicate that S100A7, SERPINB13, and PLBD1 may contribute to the inflammatory process of psoriasis by impacting macrophages infiltration, especially in LS samples." (PMID 38699235, 2024).
head and neck squamous cell carcinoma (3 papers, 2018 to 2022). A squamous cell carcinoma that arises from any of the following anatomic sites: lip and oral cavity, nasal cavity, paranasal sinuses, pharynx, larynx, and salivary glands. "As in LUSC, downregulation of SERPINB13 expression in head and neck squamous cell carcinomas was shown to associate with a poor differentiation grade of the tumors, presence of lymph node metastases and a decreased disease-free and overall survival." (PMID 30473748, 2018). "The SERPINB13-related diseases include head and neck squamous cell carcinoma, skin cancer and type I diabetes." (PMID 35559008, 2022).
gastric cancer (2 papers, 2021 to 2025). A primary or metastatic malignant neoplasm involving the stomach. "Compared with the M2 group, the metabolic interference group of gastric cancer cells led to significant differences in SERPINB13 expression in macrophages." (PMID 39991579, 2025).
head and neck cancer (2 papers, 2015 to 2019). A primary or metastatic malignant neoplasm affecting the head and neck. "Additionally, among the known IL-13 regulated genes, SERPINB13 is another legitimate candidate as its low expression has been associated with poor clinical outcome of head and neck cancers." (PMID 26208975, 2015). "Among the cross-species downregulated genes, there are two additional genes that particularly noteworthy: SERPINB13 is an angiogenesis inhibitor that is downregulated in head and neck cancers, and the neutral sphingomyelinase SMPD3 is a cell cycle regulator." (PMID 30947707, 2019).
inflammatory skin disorders (1 paper, 2021). "In parallel, SERPINB11 and SERPINB13 are human-specifically downregulated, while kallikrein 14, a major player in wound healing and inflammatory skin disorders, is upregulated more than 100 fold." (PMID 35154781, 2021).
lung carcinoma (1 paper, 2009). "BICD2, CDA, NMNAT2, SERPINB13, and TOX3 have no specificity to either AC or SCC but to lung cancer." (PMID 19761563, 2009).
lymph node metastasis (1 paper, 2014). "SERPINB13 was involved in a set of proteins that could be used for prediction of lymph node metastasis." (PMID 28250389, 2014).
melanoma (1 paper, 2011). A malignant, usually aggressive tumor composed of atypical, neoplastic melanocytes. "For melanoma progression category (T3, T4 and MM), only genes ontologically-related to hKLKs (EVPL, KLK6, KLK7, KLK8, KLK13 and SERPINB13) showed a positive and high correlation coefficient (mean of 0.971) in T4 thick melanomas (depth > 4.0 mm), but not in metastatic tumors (MM)." (PMID 22032772, 2011).
metastatic cancer (1 paper, 2017). A carcinoma which has spread from the original site of growth to another anatomic site. "These included genes which are implicated in inflammation and inflammatory responses to cancer (PTX3, IL8, TNFSF10, SERPINB13 and ANKRD1) and those involved in cell adhesion, cell migration and ECM degradation of importance in metastatic cancer (MMP12, MMP1 and ADAM19)." (PMID 28555042, 2017).
prostate carcinoma (1 paper, 2023). A carcinoma that arises from epithelial cells of the prostate gland. "An earlier study showed KRT80, RUNX, GATA6, SERPINB13, and SLC6a14 are important markers for prostate cancer progression, whereas we also identified KRT80, RUNX as well as GATA2, GATA2-AS1 in our study." (PMID 37476073, 2023).
pterygium (1 paper, 2009). A wedge-shaped fibrovascular lesion arising from the bulbar conjunctiva and extending to the cornea. "Other up-regulated proteins like small proline rich protein 1B (SPRR1B), CD24, S100 calcium binding protein, SPARC, TFF1, SPRR1B and SERPINB13 also govern the wound healing process and cornification of epithelium, again, supporting the hypothesis of aberrant wound response in pterygium." (PMID 19272163, 2009).
sarcoma (1 paper, 2019). A usually aggressive malignant neoplasm of the soft tissue or bone. "On the other hand, the finding that the angiogenesis-inhibiting gene SERPINB13 is expressed at lower levels in soft-tissue sarcoma vs. normal tissue is not surprising, given the strong evidence for the role of the neovasculature in supporting sarcoma tumor progression." (PMID 30947707, 2019).
squamous cell carcinoma (1 paper, 2025). A carcinoma arising from squamous epithelial cells. "Moreover, an association between SERPINB13 gene expression and squamous cell carcinoma was found." (PMID 40243422, 2025).
SERPINB13 also shares sentences with these, for which no sentence is quoted: cancer (4 papers); tumor (2); type 1 diabetes (2); adenocarcinoma (1); amoebiasis (1); breast carcinoma (1); cervical cancer (1); Human papillomavirus infection (1); infection (1); metastatic tumors (1); skin cancer (1).